POP5 (POP5 ribonuclease P/MRP subunit)
Description:
Component of ribonuclease P, a protein complex that generates mature tRNA molecules by cleaving their 5'-ends. Also a component of the MRP ribonuclease complex, which cleaves pre-rRNA sequences.
Synonyms: hPop5; HSPC004; RPP2; RPP20
Tractability: PROTAC: ubiquitination databases record sites on it.
Gene: Protein-coding gene on chromosome 12 (120,578,764 to 120,581,411, reverse strand). Ensembl gene ENSG00000167272.
Subcellular location: Nucleus, nucleolus
Subcellular location (Human Protein Atlas): Nucleoplasm; Nucleoli
Pathways (Reactome):
Metabolism of RNA: tRNA processing in the nucleus
Gene Ontology:
Molecular function: protein binding; ribonuclease P activity; ribonuclease P RNA binding
Biological process: tRNA 5'-leader removal; RNA processing; tRNA processing
Cellular component: multimeric ribonuclease P complex; nucleolar ribonuclease P complex; nucleolus; nucleoplasm; ribonuclease MRP complex; nucleus; ribonuclease P complex
Genetic constraint (gnomAD): Loss-of-function variants: 19 observed, 23.17 expected, observed/expected ratio (o/e) 0.82, 90% interval 0.57 to 1.2. The upper end of that interval is the gene's LOEUF score, 1.2, which puts it in group 5 of 6, group 1 being the genes least tolerant of losing a copy. Missense variants: 181 observed, 196.12 expected, observed/expected ratio (o/e) 0.92, 90% interval 0.82 to 1.04. Synonymous variants: 81 observed, 77.52 expected, observed/expected ratio (o/e) 1.04, 90% interval 0.87 to 1.26.
Homologues: Orthologues: chimpanzee POP5 (100% identical), macaque POP5 (100% identical), pig POP5 (93% identical), guinea pig POP5 (92% identical), rabbit POP5 (91% identical), dog POP5 (91% identical), mouse Pop5 (90% identical), rat Pop5 (89% identical), tropical clawed frog pop5 (58% identical), zebrafish pop5 (48% identical), Drosophila melanogaster Pop5 (27% identical), Caenorhabditis elegans popl-5 (21% identical).
Diseases named in the same sentence as POP5 in open-access papers:
POP5 is named in the same sentence as 3 diseases in open-access papers, as found by Europe PMC text mining. Sharing a sentence is not in itself a finding about the gene and the disease. The quoted sentences say what the papers report.
prostate carcinoma (1 paper, 2022). A carcinoma that arises from epithelial cells of the prostate gland. "Noncoding transcripts POP5 plays a significant role in the processing of tRNA and studies have shown that it is a new biomarker for prostate cancer." (PMID 36262474, 2022).
cancer (1 paper, 2022). A tumor composed of atypical neoplastic, often pleomorphic cells that invade other tissues. "The seven hub RBPs CD3EAP, POP5, NOP10, ATXN1, ZC3H12C, RBPMS, and SBDS were implicated in the progression and prognosis of many cancers." (PMID 36262474, 2022).
tumor (1 paper, 2022). "Compared to normal samples, ATXN1, RBPMS, SBDS, and ZC3H12C were downregulated, and CD3EAP, NOP10, and POP5 were upregulated in UCEC tumor samples." (PMID 36262474, 2022). "CD3EAP, NOP10, and POP5 were significantly up-regulated in tumor tissue samples, while ATXN1, RBPMS, SBDS, and ZC3H12C were significantly downregulated in tumor tissue samples calculating by DESeq2 and edgeR, which were consistent with our previous results." (PMID 36262474, 2022).